TRIM43 (tripartite motif containing 43)
Description:
E3 ligase that regulates nuclear lamina integrity and the association of viral chromatin with transcriptionally-active host chromatin. Acts thereby as a herpesvirus-specific antiviral factor and mediates the ubiquitination-dependent proteasomal degradation of PCNT.
Synonyms: TRIM43A
Tractability: No criterion of Open Targets' tractability assessment is met for any kind of drug.
Gene: Protein-coding gene on chromosome 2 (95,592,001 to 95,599,778, forward strand). Ensembl gene ENSG00000144015.
Subcellular location: Cytoplasm, cytoskeleton, microtubule organizing center, centrosome
Gene Ontology:
Molecular function: protein binding; ubiquitin protein ligase activity; zinc ion binding
Biological process: innate immune response; regulation of gene expression
Cellular component: cytoplasm; centrosome
Genetic constraint (gnomAD): Loss-of-function variants: 12 observed, 27.03 expected, observed/expected ratio (o/e) 0.44, 90% interval 0.28 to 0.72. The synonymous counts are far from expectation, so gnomAD's model fits this gene poorly and the ratio says little. Missense variants: 181 observed, 272.11 expected, observed/expected ratio (o/e) 0.67, 90% interval 0.59 to 0.75. Synonymous variants: 63 observed, 89.67 expected, observed/expected ratio (o/e) 0.7, 90% interval 0.57 to 0.87.
Homologues: Orthologues: rat Trim43a (47% identical), mouse Trim43c (42% identical), mouse Trim43a (41% identical), mouse Trim43b (41% identical). Paralogues in human: TRIM43B (99% identical), TRIM49C (53% identical), TRIM49 (53% identical), TRIM49B (53% identical), TRIM51 (52% identical), TRIM49D1 (52% identical), TRIM49D2 (52% identical), TRIM51G (50% identical), TRIM77 (48% identical), TRIM64 (48% identical), TRIM64B (48% identical), TRIM64C (47% identical), and 68 more.
Diseases named in the same sentence as TRIM43 in open-access papers:
TRIM43 is named in the same sentence as 2 diseases in open-access papers, as found by Europe PMC text mining. Sharing a sentence is not in itself a finding about the gene and the disease. The quoted sentences say what the papers report.
herpesvirus infection (3 papers, 2023 to 2025). "TRIM43 is unique in that it is expressed at very low levels in uninfected cells; however, after herpesvirus infection, TRIM43 transcript and protein levels are drastically upregulated, which is mediated by the transcription factor DUX4 (Double Homeobox 4)." (PMID 39599852, 2024). "Interestingly, previous studies have shown that herpesvirus infection induces TRIM43 in a DUX4-dependent manner and that TRIM43 restricts herpesvirus replication." (PMID 41211819, 2025). "For example, centrosomal protein TRIM43 is robustly induced by herpesvirus infection (but not interferons) and potently restricts a broad range of herpesviruses by regulating nuclear lamina integrity." (PMID 37010434, 2023).
HCMV infection (1 paper, 2022). "Transcripts specifically induced by HCMV infection of TOs included H3Y1 (H3.Y Histone 1), KHDC1L (KH Domain Containing 1 Like), several members of the PRAME Family (PRAMEF2, 8, 12, 14, and 20), and TRIM49A and B (Tripartite Motif Containing 43)." (PMID 35975985, 2022).